CTLA4 (cytotoxic T-lymphocyte associated protein 4)
Diseases named in the same sentence as CTLA4 in open-access papers (continued):
Sharing a sentence is not in itself a finding about the gene and the disease.
atherosclerosis (continued). "The pro-atherogenic role of IL-17A has been confirmed by multiple experiments, and future studies are needed to further prove whether CTLA-4 inhibition can influence the progression of atherosclerosis through the CXCR4/Th17/IL17A axis." (PMID 40821806, 2025). "Although, a 2013 study that increased CTLA-4 activity using abatacept in APOE 3-leiden mice found a reduction in the severity of atherosclerosis through a dramatic 78.1% decrease in arterial thickening, thus offering a different avenue for ICI therapy in atherosclerosis treatment." (PMID 40552286, 2025). "Preclinical studies on the role of CTLA-4, PD-1, and PD-L1/2 in atherosclerosis." (PMID 38473748, 2024). "Mice treated with CTLA-4 analogue (abatacept) had a reduction in femoral arteries atherosclerosis formation by 78%, also in murine models with a decreased expression of CTLA-4 membrane expression; on the contrary, anti-CTLA-4 drugs are related to a plaque progression." (PMID 38004268, 2023). "Their results suggested that short-term antibody-mediated inhibition of CTLA-4 accelerates the progression of atherosclerosis by inducing T cells to drive an inflammatory response, resulting in the formation of plaques with larger necrotic cores and less collagen." (PMID 36742069, 2023). "In addition, CTLA4 drives or inhibits plaque inflammation as a critical protein in regulating atherosclerosis." (PMID 36970364, 2023). "CTLA-4-dependent suppression of DC function by Tregs may also be involved in the reduction in atherosclerosis." (PMID 34945203, 2021). "Whether the antibody-mediated inhibition of CTLA4 affects atherosclerosis is incompletely understood and nowadays is particularly relevant, as antagonistic CTLA4 antibodies are increasingly used in cancer patients." (PMID 32872393, 2020). "Several factors may have contributed to the aggravation of atherosclerosis upon the antibody-mediated inhibition of CTLA4." (PMID 32872393, 2020). "However, antibody-mediated inhibition of CTLA-4 and PD-1 aggravated T cell–driven inflammation in atherosclerotic plaques of hyperlipidemic mice and provoked the progression of atherosclerosis toward a clinically unfavorable plaque phenotype." (PMID 34396271, 2020). "Experimental studies have also identified a role for CTLA4 in atherosclerosis." (PMID 32872393, 2020). "Therefore, we evaluated the effects of the antibody-mediated inhibition of CTLA4 on experimental atherosclerosis in hyperlipidemic mice." (PMID 32872393, 2020). "Considering that the Th1 immune response promotes atherosclerosis, our findings suggest that intervention to enhance CTLA-4 function could be an attractive strategy to treat patients with AAA who are at high risk of atherosclerotic cardiovascular disease." (PMID 31147569, 2019). "Although a possible role of the coinhibitory molecule CTLA-4 in the protection against atherosclerosis has been suggested, its role in the development of atherosclerosis-related cardiovascular diseases such as AAA remains completely unknown so far." (PMID 31147569, 2019). "Therefore, the CTLA-4 pathway appears to be crucial in modulating atherosclerosis." (PMID 38473748, 2024). "Thus, in initial atherosclerosis, anti-CTLA4 treatment may indirectly increase the endothelial adhesion molecule expression by aggravating systemic and vascular T cell-driven inflammatory responses." (PMID 32872393, 2020). "However, it is unknown whether CTLA-4 plays a protective role in the development of atherosclerosis-related cardiovascular diseases such as AAA." (PMID 31147569, 2019). "The interaction between CTLA-4 and CD80/CD86 binding appears to have immunoregulatory effects that suggest a protective role in atherosclerosis." (PMID 38375475, 2024).
atherosclerosis (continued). "Specifically, substantial foundational cellular and animal studies indicate that the immune checkpoint proteins such as CTLA-4, PD-1, PD-L1, and LAG-3 serve as crucial negative regulators of atherosclerosis." (PMID 38375475, 2024). "Abatacept, a syngeneic analog of CTLA‐4, prevented CD4+ T‐cell activation and reduced atherosclerosis progression by 78% in the femoral artery of mice." (PMID 37584246, 2023). "All these data show that CTLA4 inhibited plaque development by generating anti-inflammatory T cell responses, whereas CD80/86-CD28 co-stimulation promoted atherosclerosis by eliciting Th1 responses." (PMID 36703734, 2022). "Comparable to PD-1/PD-L1, CTLA-4 knockout mice show increased lesion size, and mice receiving anti-CTLA-4 blocking antibodies showed increased progression of atherosclerosis mainly driven by T-cell-induced inflammation." (PMID 36263134, 2022). "Whether ICI therapy targeting CTLA4 induces similar changes in plaque inflammation in cancer patients is currently unknown and should be investigated in future clinical studies, as our study demonstrates that the inhibition of CTLA4 accelerates the progression of experimental atherosclerosis." (PMID 32872393, 2020). "Tregs limit the CD80/CD86–CD28-dependent activation of T cells through CTLA-4-dependent downregulation of CD80 and CD86 expression on DCs, which may contribute to the reduction in atherosclerosis." (PMID 40608058, 2025). "Several preclinical studies suggest that the CTLA-4, PD-1/PD-L1, and LAG-3 pathways play a protective role in atherogenesis, whereas their blockade may contribute to atherosclerosis progression." (PMID 41009661, 2025). "Similarly, another preclinical study on hypercholesterolemic ApoE3*Leiden mice showed that administration of anti-CTLA-4 increased vascular lesion size, whereas abatacept, a soluble CTLA-4Ig fusion protein, reduced atherosclerosis development." (PMID 41009661, 2025). "CTLA-4-Ig that binds to CD80 and CD86 and has an inhibitory effect on the CD80/CD86–CD28 costimulation pathway is clinically effective in treating rheumatoid arthritis, and has also been shown to protect against experimental atherosclerosis." (PMID 34945203, 2021). "As 18F-FDG PET is widely used to analyze monocyte/macrophage-driven vascular and systemic inflammation in atherosclerosis, these data indicate that the antibody-mediated inhibition of CTLA4 did not affect the monocyte/macrophage-driven inflammation." (PMID 32872393, 2020). "We here show that antibody-mediated inhibition of CTLA-4 and PD-1 aggravated plaque inflammation, characterized by a marked increase in cytotoxic CD8+ T cells, and increased necrotic core formation, which resulted in the development of more advanced atherosclerosis (Central Illustration)." (PMID 34396271, 2020). "Extensive basic cellular and animal data strongly support that the immune checkpoint proteins targeted in ICI therapies (CTLA-4, PD-1, PD-L1, and LAG-3) serve as critical negative regulators of atherosclerosis." (PMID 39023770, 2025).
renal carcinoma (38 papers, 2013 to 2025). A carcinoma arising from the epithelium of the renal parenchyma or the renal pelvis. "Another preclinical study showed that the combination of anti-PD-1 and anti-CTLA-4 antibodies with CIK cells exerts synergistic antitumor effects on renal cancer cells." (PMID 40539041, 2025). "As shown in the results, the expression levels of immune checkpoints were differential in different groups, especially PD-1, CTLA4 and LAG3, which are commonly found in renal cancer, were more significantly expressed in the high-risk group." (PMID 38546385, 2024). "At present, immune checkpoint blockade therapy (PD-1, PD-L1, and CTLA4) has been successfully applied to renal cancer patients with certain results." (PMID 36003341, 2022). "For comparison, early in the development of CTLA4 inhibitors, Rosenberg and colleagues evaluated ipilimumab monotherapy in the treatment of renal cancer." (PMID 30374524, 2019). "This suggests that renal cancer patients with higher Wnt scores might particularly benefit from CTLA-4 targeted treatments, potentially leading to improved survival outcomes." (PMID 40002717, 2025). "In addition, TAMs infiltrated by human renal cancer can upregulate COX-2 and increase the expression of cytotoxic T-lymphocyte-associated protein-4 (CTLA-4) and forkhead box protein 3 (Foxp3)." (PMID 37004014, 2023). "In addition, by analyzing gene expression profiles from renal cancer-bearing mice treated with an anti-PD-L1 and anti-CTLA-4 combination therapy, we confirmed that renal cancer-bearing mice responding to immunotherapy had a lower level of ARHGAP11A." (PMID 37175461, 2023). "Previous studies in renal cancer have demonstrated that immunotherapy aimed at Treg depletion, such as anti-CTLA4 and anti-CD25, could enhance local anti-tumor response and induce an abscopal effect." (PMID 35566403, 2022). "In renal cancer-bearing mice, the ARHGAP11A low-level group responded more effectively to anti-PD-L1 plus anti-CTLA-4 immunotherapy." (PMID 37175461, 2023). "Anti(α)-CTLA-4 monotherapy has not been FDA approved for use in advanced renal cancer patients, due to a lack of demonstrated efficacy." (PMID 34064933, 2021).
urothelial carcinoma (35 papers, 2016 to 2025). A malignant neoplasm derived from the transitional epithelium of the urinary tract (urinary bladder, ureter, urethra, or renal pelvis). "The Cytotoxic T-Lymphocyte Antigen-4 (CTLA-4) gene is suspected to be a susceptibility gene in urothelial carcinoma." (PMID 38046481, 2023). "This is the first study examining the association between CTLA-4 -318C/T polymorphism and urothelial carcinoma in Japanese patients." (PMID 38046481, 2023). "Ipilimumab, a CTLA-4 antibody, may be considered for patients diagnosed with operable high-risk urothelial carcinoma who are ineligible for cisplatin treatment and have a low calculated risk score according to this model." (PMID 38305808, 2024). "Key immune checkpoint proteins PD-1 and CTLA-4 are frequently expressed on T-cells in urothelial carcinoma." (PMID 38201559, 2023). "Within epithelial tumors, the density of CTLA-4+ cells was higher in squamous cell (421 ± 469 cells/mm2) and urothelial carcinomas (418 ± 347 cells/mm2) than in adenocarcinomas (268 ± 375 cells/mm2) and renal cell neoplasms (256 ± 269 cells/mm2)." (PMID 35091676, 2022). "Immune checkpoint inhibitors (ICI) targeting CTLA-4, PD-1 or PD-L1 have provided clinical benefit, particularly in renal cell and urothelial carcinoma, and have been incorporated into standard of care treatment in both localized and metastatic settings." (PMID 34771578, 2021). "In patients with urothelial carcinoma, treatment with anti-CTLA-4 preoperatively resulted in increased frequency of CD4 + ICOShi T cells, which was then retrospectively shown to correlate with overall survival for metastatic melanoma patients." (PMID 32111080, 2020). "Currently, durvalumab is also under investigation in the Phase III ‘DANUBE’ trial as a first-line treatment in urothelial carcinoma as monotherapy and in combination with the CTLA-4 inhibitor, tremelimumab." (PMID 30975211, 2019). "The coexpression of activation molecules (HLA-DR, CD38) and co-inhibitory molecules (PD-1, CTLA-4) represents the T cell exhaustion, the results showed that almost all clusters had exhaustion phenotype in the immune microenvironment of urothelial carcinoma tissues." (PMID 35725444, 2022).
Arthritis (33 papers, 2009 to 2025). Inflammation of a joint. "In early‐stage arthritis, co‐administration with cytotoxic T‐lymphocyte‐associated protein (CTLA)‐4‐Ig, clinically known as abatacept, delayed disease progression and sustained the reduction of mechanical allodynia." (PMID 41244342, 2025). "In combination with the cytotoxic T‐lymphocyte‐associated protein 4 immunoglobulin G (CTLA‐4‐Ig) DMARD in early‐stage arthritis, ATRA‐PLGA MP controlled disease and modified pain." (PMID 41244342, 2025). "For example anti‐PD1/PDL1 monotherapy commonly causes a small joint arthritis whereas in combination with anti‐CTLA4 a large joint mono/oligoarthritis is more common." (PMID 37435963, 2023). "In CTLA4‐deficient mice, alongside multiorgan inflammation particularly of the heart and lungs, mice occasionally develop arthritis and vasculitis." (PMID 37435963, 2023). "Arthritis-irAE is associated with either PD-1 inhibitor monotherapy or combination of CTLA-4 and PD-1 inhibitor therapy." (PMID 35413951, 2022). "A summary of 14 CTLA-4 deficiency patients show arthritis prevalence of 14%." (PMID 31847838, 2019). "Our previous work identified increased CTLA‐4 expression in joint‐localized dendritic cells and CD4+ T cells following nanoparticle treatment, which was associated with reduced arthritis severity and protection against bone and cartilage damage." (PMID 41244342, 2025). "Based on these findings, we evaluated the efficacy of ATRA‐PLGA MP at the early stage of arthritis, benchmarking it against CTLA‐4‐Ig and assessing the potential for added therapeutic benefit with combination therapy." (PMID 41244342, 2025). "Our analyses reveal that Th1-CD8+ T cells play a pivotal role in arthritis-irAE disease pathogenesis, and Th17 cells and transient Th17 cells, enriched in arthritis after combined CTLA-4 and PD-1 inhibitor therapy, are involved in steroid resistance." (PMID 35413951, 2022). "It has therefore been used widely in the treatment of irAE-arthritis (from CTLA-4, PD-1, or PD-L1 inhibitors alone or in combination) in patients in whom from glucocorticoids cannot be tapered successfully." (PMID 36081549, 2022). "Hydroxychloroquine has also been used successfully in the treatment of IR-arthritis (from CTLA-4 inhibitor and/or a PD-1/PD-L1 inhibitor)." (PMID 36081549, 2022). "On the other hand, when CTLA-4 Ig was injected 3 weeks after the onset of arthritis, lymphatic drainage of CTLA-4 Ig was reduced." (PMID 32778803, 2020). "When CTLA-4 Ig was injected 3 days after the onset of arthritis, CTLA-4 Ig showed extravasation and started to drain via the lymphatic vessels immediately after injection." (PMID 32778803, 2020). "It has been inferred that immune system inactivation by CTLA-4-Ig strongly supplements the difference in the amount of Treg and that the influence of endogenous Treg in arthritis is reduced." (PMID 31747403, 2019). "Abatacept, a recombinant protein that combines the extracellular region of CTLA-4 and human IgG, has been applied as a biopharmaceutical for treating arthritis and juvenile idiopathic arthritis." (PMID 31665022, 2019). "Higher arthritis disease activity was positively correlated with CTLA4, CD28 and CD45RA and negatively correlated with CCR7 in 2019, which was a mean of about 4 years post-infection that was not conserved in 2021, which was a mean of about six-years post-infection." (PMID 38873035, 2024). "CTLA-4-Ig improved arthritis in terms of clinical score and incidence, compared with hIgG." (PMID 36180526, 2022). "Furthermore, arthritis after combined CTLA-4 and PD-1 inhibitor therapy preferentially has enhanced Th17 and transient Th1/Th17 cell signatures." (PMID 35413951, 2022). "We have also followed a family in which the newborn CTLA4-mutated child developed severe recalcitrant arthritis at the age four months, having had no obvious infection other than the live rotavirus immunization." (PMID 36405723, 2022).
Arthritis (continued). "Finally, given that CTLA-4 is constitutively expressed, it would also be an important topic to compare Treg biology between PD-1 inhibitor arthritis-irAE and combined ICI arthritis-irAE." (PMID 35413951, 2022). "Variants of CTLA4-Ig, abatacept and belatacept are FDA approved as immunosuppressive agents in arthritis and transplantation, yet murine studies suggested that CTLA4-Ig could be beneficial in a number of other diseases." (PMID 25860138, 2015). "Our previous work also identified increased CTLA‐4 expression in joint‐localized dendritic cells and CD4+ T cells following treatment with calcitriol‐loaded nanoparticles, which was associated with reduced arthritis severity and protection against bone and cartilage damage." (PMID 41244342, 2025). "However, this inhibition was neutralized when the mice received a combination of anti-PD-1 and anti-CTLA-4 mAbs, exacerbating arthritis; this suggests that while ICIs effectively activate the immune system to battle tumors, they also significantly increase the risk of irAEs, such as arthritis." (PMID 41239350, 2025). "Interestingly, CTLA‐4‐Ig monotherapy and combination therapy exhibited a similar trend to the control IgG group by day 4, despite providing strong protection against clinical arthritis symptoms." (PMID 41244342, 2025). "Besides, function experiments in vivo indicated that gene delivery of CTLA4 by intra-articular injection could alleviate experimental arthritis." (PMID 34339393, 2021). "The combination of CTLA‐4‐Ig and ATRA‐PLGA MP treatment improved arthritis control, with lower average clinical scores than other groups throughout the experiment." (PMID 41244342, 2025). "In combinationwith CTLA-4 IgG, Agg-CLNP durably reduced arthritis onset and severityin SKG mice, significantly more than CTLA-4 IgG alone." (PMID 41019102, 2025). "In contrast to CTLA-4 inhibitors, TIM-3 inhibition may offer reduced risks of arthritis but comparable potential for oral irAEs due to innate immune disruption." (PMID 41239350, 2025). "CTLA‐4‐Ig, a widely used biologic DMARD that operates by competitively inhibiting the CD28‐CD80/86 co‐stimulatory pathway, has been shown to have potential for preventing arthritis in clinical trials." (PMID 41244342, 2025). "Taken together, we speculate that in combined ICI arthritis, steroid-resistant Th17 cells, differentiated by CTLA-4 inhibitor therapy, might undergo plasticity into Th1 cells, which in turn help CD8+ T cells in arthritis-irAE." (PMID 35413951, 2022). "With regard to other antineoplastic agents, IA arthritis has been more frequently observed as a side effect of anti-PD-1 ICI agents, and it may also develop after the administration of anti-CTLA-4 antibodies." (PMID 32150095, 2020). "However, in CTLA4-Ig-untreated DC-transferred CIA mice, arthritis developed and then progressed rapidly." (PMID 21414236, 2011). "Arthritis develops due to the lack of immune regulation resulting from CTLA-4 and PD-1/PD-L1 suppression, leading to unchecked T-cell responses, elevation of IL-17 and TNF-α, and infiltration of effector memory CD8+ T-cells into the synovium, which differentiates it from autoantibody-mediated RA." (PMID 41239350, 2025). "Furthermore, CTLA-4-Ig was effective at inhibiting the TNF-induced osteoclast formation in a non-T cell-dependent TNF-induced model of arthritis, as well as at inhibiting the formation of inflammatory bone erosions in vivo." (PMID 19930661, 2009).